JAGN1 (jagunal vesicle mediated transporter 1)
Description:
Endoplasmic reticulum transmembrane protein involved in vesicle-mediated transport, which is required for neutrophil function. Required for vesicle-mediated transport; it is however unclear whether it is involved in early secretory pathway or intracellular protein transport. Acts as a regulator of neutrophil function, probably via its role in vesicle-mediated transport: required for defense against fungal pathogens and for granulocyte colony-stimulating factor (GM-CSF) signaling pathway; possibly by regulating glycosylation and/or targeting of proteins contributing to the viability and migration of neutrophils.
Synonyms: GL009; FLJ14602; SCN6
Tractability: Small molecule: a structure with a bound ligand is known. Antibody: UniProt predicts a signal peptide or a membrane-spanning region. PROTAC: ubiquitination databases record sites on it; its protein half-life has been measured.
Gene: Protein-coding gene on chromosome 3 (9,890,574 to 9,894,349, forward strand). Ensembl gene ENSG00000171135.
Subcellular location: Endoplasmic reticulum membrane
Subcellular location (Human Protein Atlas): Vesicles
Gene Ontology:
Molecular function: protein binding
Biological process: granulocyte colony-stimulating factor signaling pathway; neutrophil differentiation; vesicle-mediated transport; endoplasmic reticulum organization; exocytosis; defense response to fungus; negative regulation of insulin secretion involved in cellular response to glucose stimulus; neutrophil mediated immunity; neutrophil migration
Cellular component: endoplasmic reticulum; endoplasmic reticulum membrane
Genetic constraint (gnomAD): Loss-of-function variants: 10 observed, 15.97 expected, observed/expected ratio (o/e) 0.63, 90% interval 0.38 to 1.06. The upper end of that interval is the gene's LOEUF score, 1.06, which puts it in group 4 of 6, group 1 being the genes least tolerant of losing a copy. Missense variants: 252 observed, 238.23 expected, observed/expected ratio (o/e) 1.06, 90% interval 0.95 to 1.17. Synonymous variants: 110 observed, 94.29 expected, observed/expected ratio (o/e) 1.17, 90% interval 1 to 1.37.
Homologues: Orthologues: chimpanzee JAGN1 (99% identical), macaque JAGN1 (99% identical), dog JAGN1 (98% identical), guinea pig JAGN1 (98% identical), mouse Jagn1 (98% identical), rat Jagn1 (98% identical), rabbit JAGN1 (96% identical), zebrafish jagn1a (74% identical), zebrafish jagn1b (72% identical), Drosophila melanogaster jagn (32% identical), Caenorhabditis elegans K05C4.2 (31% identical).
Diseases named in the same sentence as JAGN1 in open-access papers:
JAGN1 is named in the same sentence as 37 diseases in open-access papers, as found by Europe PMC text mining. Sharing a sentence is not in itself a finding about the gene and the disease. The quoted sentences say what the papers report.
congenital neutropenia (10 papers, 2018 to 2024). "One of the patients with neutropenia was known to have a variant in the JAGN1 gene by sequencing techniques, associated with severe congenital neutropenia." (PMID 38790188, 2024). "Severe congenital neutropenia caused by jagunal homolog 1 (JAGN1) mutation is a rare condition resulting from maturation arrest secondary to endoplasmic reticulum stress response from impaired neutrophil protein glycosylation." (PMID 37528877, 2023). "We also review the literature for other cases of congenital neutropenia resulting from JAGN1 deficiency." (PMID 37528877, 2023). "One patient with severe congenital neutropenia carried compound heterozygous mutation in the JAGN1 gene." (PMID 30697212, 2018). "Homozygous or compound heterozygous mutations in JAGN1 cause severe congenital neutropenia." (PMID 39286252, 2024). "JAGN1 mutation is one of the rare genetic mutations responsible for severe congenital neutropenia (SCN)." (PMID 37120535, 2023). "Patients with severe congenital neutropenia (SCN) have mutations in the gene for jagged 1 protein, (JAGN1)." (PMID 36034717, 2022). "In patients affected by biallelic JAGN1 mutation leading to severe congenital neutropenia (SCN), N-glycosylation of proteins in neutrophils is perturbed leading to a reduced number of galactosylated antennae and a reduced amount of antennary fucose residues." (PMID 29651288, 2018). "Genetic variants in G6PC3, JAGN1, and VPS13B affect the number and function of neutrophils (rather than their migration) which consequently cause different forms of severe congenital neutropenia (SCN)." (PMID 38550576, 2024). "A patient with JAGN1 gene mutation suffering from Severe Congenital Neutropenia (SCN)." (PMID 29996795, 2018).
neutropenia (10 papers, 2016 to 2026). A decrease in the number of neutrophils found in the blood. "More recently, the Jagn1 gene has been shown to be mutated in patients with a rare form of neutropenia and shown to play a role in the secretory pathway, since certain cell surface receptors such as the G-CSF receptor are reduced in patient neutrophil cells." (PMID 26882284, 2016). "One potential explanation may be the presence of deficient N-glycosylation of the G-CSF receptor in patients with JAGN1-associated neutropenia, which has been suggested to contribute to inefficient G-CSF-R mediated signaling and thus G-CSF unresponsiveness." (PMID 39286252, 2024). "Case reports of severe congenital neutropenia caused by the JAGN1 mutation." (PMID 37528877, 2023). "The remaining 10 patients have JAGN1 deficiency (n = 1); poikiloderma with neutropenia (n = 1); cystic fibrosis (n = 1); leukocyte adhesion deficiency type 3 (n = 1); GATA2 deficiency (n = 1); undefined leukopenia (n = 1); and unspecified phagocytic diseases (n = 4)." (PMID 37559153, 2023). "In a murine, hematopoietic JAGN1 knockout model, which displays susceptibility to Candida albicans infection in the absence of neutropenia, treatment with granulocyte-macrophage-CSF (GM-CSF) was able to restore the functional defect of neutrophils." (PMID 39286252, 2024). "While G6PC3- and JAGN1-CDG show persistent neutropenia and bone marrow defects, VPS13B-CDG presents intermittent decreased neutropenia with normal bone marrow development and cellularity." (PMID 38550576, 2024).
abscess (2 papers, 2023). An inflammatory process characterized by the accumulation of pus within a newly formed tissue cavity which is the result of a bacterial, fungal, or parasitic infection or the presence of a foreign body. "The other clinical features of our patients, like recurrent abscess formation, otitis media, pneumonia, and lymphadenopathies, are identical to other registered patients with JAGN1 mutations." (PMID 37120535, 2023). "Common clinical features associated with the mutation were sepsis, abscess, pneumonia, failure to thrive, and neurodevelopmental delay, and genetic defects were homozygous mutations in exons 1 and 2 of JAGN1 in addition to the alteration of proteins." (PMID 37528877, 2023).
intracranial hemorrhage (2 papers, 2023 to 2024). Bleeding within the SKULL, including hemorrhages in the brain and the three membranes of MENINGES. "In addition, one JAGN1-mutant SCN patient with bleeding abnormalities and recurrent intracranial hemorrhage has also been reported." (PMID 39286252, 2024).
pneumonia (2 papers, 2023). An acute, acute and chronic, or chronic inflammation focally or diffusely affecting the lung parenchyma, caused by an infection in one or both of the lungs (by bacteria, viruses, fungi, or mycoplasma.). "The previously reported Iranian patient with JAGN1 mutation was a girl from consanguineous parents who presented pneumonia, upper respiratory tract infection, skin abscess, and focal epilepsy with the same genetic mutation." (PMID 37120535, 2023).
epidural abscess (1 paper, 2023). Circumscribed collections of suppurative material occurring in the spinal or intracranial epidural space. "In this study Here, we report that an invasive epidural abscess caused by P. aeruginosa occurred in a patient with SCN secondary to JAGN1 mutation, who initially presented with periorbital cellulitis." (PMID 37528877, 2023).
Immunodeficiency (1 paper, 2023). Failure of the immune system to protect the body adequately from infection, due to the absence or insufficiency of some component process or substance. "The mutated JAGN1 is responsible for immunodeficiency related to innate and humoral defense mechanisms." (PMID 37120535, 2023).
insulinoma (1 paper, 2016). "Jagn1 mRNA was also increased in response to tunicamycin, an inhibitor of N-linked glycosylation known to induce ER stress, in insulinoma cells and in isolated primary mouse islets." (PMID 26882284, 2016). "The Jagn1 protein was indentified in a SILAC proteomic screen of proteins that are increased in insulinoma cells expressing a folding-deficient proinsulin." (PMID 26882284, 2016). "We also validated that Jagn1 mRNA is increased in insulinoma cells by conditions that cause moderate to severe ER stress including production of misfolded proinsulin and tunicamycin treatment." (PMID 26882284, 2016). "Importantly however, overexpression of Myc-tagged Jagn1 in insulinoma cells caused the opposite effect; i.e. a reduction in steady-state proinsulin and insulin levels." (PMID 26882284, 2016). "In a SILAC proteomic screen we identified Jagn1 as a protein whose levels were increased in an insulinoma cell model of misfolded proinsulin induced ER stress." (PMID 26882284, 2016). "We confirmed that Jagn1 mRNA is detected in rodent islets and insulinoma cells, and that expression of this gene appears to be ubiquitous." (PMID 26882284, 2016). "In contrast, overexpression of Jagn1 in insulinoma cells resulted in reduced cellular proinsulin and insulin levels." (PMID 26882284, 2016). "Jagn1 mRNA was detected in primary rodent islets and in insulinoma cell lines and the levels were increased in response to ER stress." (PMID 26882284, 2016). "To determine if Jagn1 is an ER stress response gene, we performed real-time PCR analysis and indeed, in line with the SILAC proteomic results, Jagn1 mRNA was significantly increased in insulinoma cells expressing mutant proinsulin." (PMID 26882284, 2016). "The function of Jagn1 was assessed in insulinoma cells by both knock-down and overexpression approaches." (PMID 26882284, 2016). "Using siRNA we knocked-down Jagn1 mRNA by about 60% in insulinoma cells." (PMID 26882284, 2016). "How might Jagn1 affect proinsulin translation in insulinoma cells?" (PMID 26882284, 2016). "To examine Jagn1 localization in insulinoma cells, we expressed Myc or GFP-tagged Jagn1 at the N-terminus, followed by immunofluorescence microscopy." (PMID 26882284, 2016).
rubella (1 paper, 2023). A viral infection caused by the rubella virus. "In rubella, including five in whole blood (JAGN1, RRP12, RP11-452K12.7, CASP7, and AP3S2), four in the lung tissue (IL17RC, FAM86HP, AMACR, and RRP12), and four in the transformed fibroblast cells (PPP2R1B, C11orf1, DLAT, and TMEM117)." (PMID 37020999, 2023).
infection (3 papers, 2023 to 2024). The state of being infected such as from the introduction of a foreign agent such as serum, vaccine, antigenic substance or organism. "While most types of SCN show a rise in neutrophil numbers and an associated reduction of infection episodes with G-CSF treatment, most patients with JAGN1-mutant SCN have been described as low responders to this therapy." (PMID 39286252, 2024). "Given the variability seen in the clinical presentation of patients with SCN secondary to JAGN1 deficiency, a high index of suspicion for invasive pyogenic infection should be maintained in those with this immunodeficiency." (PMID 37528877, 2023). "Here, we report a case of a patient with autosomal recessive JAGN1 deficiency leading to SCN, with recurrent infections associated with bleeding manifestations." (PMID 37528877, 2023). "Mutations in the gene encoding JAGN1 are a rare and recently identified cause of SCN characterized by recurrent infections along with bony abnormalities and a heterogeneous clinical presentation." (PMID 37528877, 2023). "This should lead to prompt initiation of treatment and prophylaxis for life-threatening infections, especially when patients with SCN secondary to JAGN1 mutation present with new focal neurologic defects, altered mental status, or have new abnormalities noted during physical examination." (PMID 37528877, 2023). "Patients with JAGN1-mutant SCN with reduced G-CSF responsiveness and elevated infection rate should be evaluated early for stem cell transplantation." (PMID 39286252, 2024). "Severe infection history and lack of therapeutic benefit by recombinant G-CSF or GM-CSF should prompt consideration of HSCT in JAGN1-mutant SCN." (PMID 39286252, 2024).
bacterial infections (1 paper, 2024). "JAGN1-mutant patients present with severe early-onset bacterial infections and most have been described as low-responders to recombinant granulocyte colony-stimulating factor (G-CSF) therapy." (PMID 39286252, 2024). "In 2014, homozygous mutations in jagunal homolog 1 (JAGN1), coding for a transmembrane protein, were found to be associated with a high risk of early onset bacterial infections due to lack of mature neutrophils." (PMID 39286252, 2024).
JAGN1 also shares sentences with these, for which no sentence is quoted: Barth syndrome (2 papers); Cohen syndrome (2); developmental delay (2); 3-methylglutaconic aciduria (1); Cyclic neutropenia (1); cystic fibrosis (1); Failure to thrive (1); focal epilepsy (1); fungal infections (1); glycogen storage disease type 1b (1); glycogen storage disease type I (1); hematologic neoplasms (1); hypospadias (1); leukocyte adhesion deficiency type II (1); leukopenia (1); lymphadenopathies (1); otitis media (1); pancreatic insufficiency (1); periodontitis (1); pheochromocytoma (1); retinal angiomas (1); Sepsis (1); skin abscess (1); stomatitis (1); undescended testis (1); upper respiratory tract infection (1).